SNX33 (sorting nexin 33)
Description:
Plays a role in the reorganization of the cytoskeleton, endocytosis and cellular vesicle trafficking via its interactions with membranes, WASL, DNM1 and DNM2. Acts both during interphase and at the end of mitotic cell divisions. Required for efficient progress through mitosis and cytokinesis. Required for normal formation of the cleavage furrow at the end of mitosis. Modulates endocytosis of cell-surface proteins, such as APP and PRNP; this then modulates the secretion of APP and PRNP peptides. Promotes membrane tubulation (in vitro). May promote the formation of macropinosomes.
Synonyms: SH3PX3; SH3PXD3C; SNX30; MGC32065
Tractability: Antibody: UniProt places it where antibodies can reach, with medium confidence; its Gene Ontology location is reachable by antibodies, with medium confidence. PROTAC: ubiquitination databases record sites on it; its protein half-life has been measured.
Gene: Protein-coding gene on chromosome 15 (75,647,912 to 75,662,301, forward strand). Ensembl gene ENSG00000173548.
Subcellular location: Cytoplasm, cytosol; Membrane; Cytoplasmic vesicle membrane
Gene Ontology:
Molecular function: identical protein binding; protein binding; phosphatidylinositol binding
Biological process: cleavage furrow formation; endocytosis; endosomal transport; endosome organization; macropinocytosis; mitotic cytokinesis; negative regulation of endocytosis; negative regulation of protein localization to cell surface; plasma membrane tubulation; positive regulation of membrane protein ectodomain proteolysis; positive regulation of protein localization to cell surface; protein import; intracellular protein transport; mitotic cell cycle; positive regulation of catabolic process; protein transport
Cellular component: cytoplasmic vesicle; cytosol; membrane; plasma membrane; cytoplasmic vesicle membrane
Genetic constraint (gnomAD): Loss-of-function variants: 19 observed, 38.13 expected, observed/expected ratio (o/e) 0.5, 90% interval 0.35 to 0.73. The upper end of that interval is the gene's LOEUF score, 0.73, which puts it in group 2 of 6, group 1 being the genes least tolerant of losing a copy. Missense variants: 641 observed, 785.11 expected, observed/expected ratio (o/e) 0.82, 90% interval 0.76 to 0.87. Synonymous variants: 246 observed, 294.39 expected, observed/expected ratio (o/e) 0.84, 90% interval 0.75 to 0.93.
Homologues: Orthologues: chimpanzee SNX33 (99% identical), macaque SNX33 (99% identical), pig SNX33 (97% identical), rat Snx33 (95% identical), mouse Snx33 (95% identical), dog SNX33 (93% identical), guinea pig SNX33 (91% identical), rabbit SNX33 (79% identical), zebrafish snx33 (74% identical), tropical clawed frog snx33 (72% identical), Drosophila melanogaster Snx1 (14% identical), Caenorhabditis elegans snx-1 (10% identical), and 2 more. Paralogues in human: SNX18 (53% identical), SNX9 (35% identical), SNX2 (16% identical), SNX30 (16% identical), SNX1 (16% identical), SNX8 (15% identical), SNX7 (14% identical), SNX4 (13% identical), SNX6 (11% identical), SNX5 (10% identical), SNX32 (9% identical), SNX12 (9% identical), and 3 more.